CLU (clusterin)
Diseases named in the same sentence as CLU in open-access papers (continued):
Sharing a sentence is not in itself a finding about the gene and the disease.
amyotrophic lateral sclerosis (8 papers, 2018 to 2024). Amyotrophic lateral sclerosis (ALS) is a neurodegenerative disease characterized by progressive muscular paralysis reflecting degeneration of motor neurons in the primary motor cortex, corticospinal tracts, brainstem and spinal cord. "The results of our study suggest elevated levels of clusterin, tau protein, and phosphorylated tau protein in the cerebrospinal fluid of patients with amyotrophic lateral sclerosis." (PMID 38184629, 2024). "Clusterin has been shown to be upregulated in the spinal cord of patients with amyotrophic lateral sclerosis (ALS) and has been shown to protect against TDP‐43 protein misfolding in animal and cell models." (PMID 31386770, 2020). "ER stress resulted in the cytoplasmic accumulation of clusterin in a Drosophila model of amyotrophic lateral sclerosis (ALS), reducing accumulation of TDP-43 protein inclusions and partially rescuing the ALS-like phenotype." (PMID 30872998, 2019). "Clusterin is a glycoprotein known to accumulate in neurons after axotomy, injury, or in neurodegenerative diseases (such as amyotrophic lateral sclerosis [ALS], Alzheimer) that was proposed to modulate cell death, autophagy, and clearance of protein aggregates or cell debris." (PMID 29768404, 2018). "In Huntington’s disease, CLU is increased in the serum of patients compared to healthy controls, and CLU is also upregulated in the CNS in amyotrophic lateral sclerosis (ALS)." (PMID 36497163, 2022). "Specific proteins, e.g., α-synuclein (α-syn) and clusterin in Parkinson ́s disease (PD); creatinine, human serum albumin (HSA), and TAR DNA binding protein 43 kDa (TDP-43) in amyotrophic lateral sclerosis (ALS); as well as RNAs’ biomarkers have been discovered in biofluids." (PMID 36614231, 2023).
Cirrhosis (8 papers, 2012 to 2022). A chronic disorder of the liver in which liver tissue becomes scarred and is partially replaced by regenerative nodules and fibrotic tissue resulting in loss of liver function. "Immunohistochemical analyses of liver tissues from 11 patients with control samples and 14 patients with cirrhosis revealed that the expression level of clusterin was upregulated in the cirrhotic condition." (PMID 31739636, 2019). "The finding pointed to the significant role of APOA1 and CLU as the common two biomarker in development of cirrhosis and HCC diseases." (PMID 28224023, 2016). "Centrality and cluster screening identified hub genes, including APOE, TTR, CLU, and APOA1 in cirrhosis." (PMID 28224023, 2016). "Serum clusterin was introduced as more specific and sensitive biomarker than AFP in distinction of HBV-cirrhosis with HCC base on HBV-cirrhosis." (PMID 28224023, 2016). "HP α and α-2 isoforms, CLU, retinol binding protein, TTR, albumin, AGP and hemoglobin delta were decreased in the cirrhosis stage but IgJ chain was increased." (PMID 24066001, 2013). "In HBV patients with cirrhosis, AGP was up regulated in three spots; also, CLU and leucine-rich α-2-glycoprotein (LRG) were up regulated and Ig gamma chain C was down regulated in this group compared to HCV cirrhosis." (PMID 24066001, 2013). "We observe lower intensities in the non-fucosylated glycopeptides of proteins (hemopexin, clusterin, ITIH4, fibrinogen) reported to decrease in cirrhosis while the non-fucosylated glycopeptide of alpha-2 macroglobulin has higher intensity in cirrhosis in line with its increased serum concentration." (PMID 34857845, 2021).
liver disease (8 papers, 2013 to 2025). "For instance, some of the complement proteins identified in this study, including C1QBP, C4BPA, CLU, and SERPING1, have also been identified in proteomic analyses as potential biomarkers in metabolic dysfunction-associated steatotic liver disease/metabolic dysfunction-associated steatohepatitis." (PMID 38573776, 2024). "There were significant differences in clusterin, PTA, WBC, NC, LC, NLR, INR, TBIL, and incidences of HE and hepatorenal syndrome between HBV-non-ACLF and HBV-ACLF patients (P < 0.05)." (PMID 33381244, 2020).
multiple sclerosis (8 papers, 2009 to 2022). A progressive autoimmune disorder affecting the central nervous system resulting in demyelination. "CLU has also been found to be associated with protein deposits found in other neurological diseases, including in both white matter disease and multiple sclerosis." (PMID 36497163, 2022). "In post-mortem tissue from multiple sclerosis patients, immunohistochemical analysis of multiple sclerosis lesions highlighted increased expression and co-localisation of CLU with complement components C1q, C3b, C4d and MAC, compared to healthy controls." (PMID 36497163, 2022). "In another study, two factors involved in complement activation, clusterin and C3, were identified in the CSF of several patients of multiple sclerosis." (PMID 28326060, 2017). "In agreement with our results, CLU mRNA levels were reported to be elevated in glial fibrillary acidic protein-positive astrocytes in white matter lesions over NAWM, but not in grey matter of multiple sclerosis patients." (PMID 32272486, 2020).
myocarditis (8 papers, 2013 to 2025). Myocarditis is a condition that is characterized by inflammation of the heart muscle (myocardium). "Deficiency of CLU gene product in aged mice increases the severity of immune response mediated myocarditis in heart and glomerulopathy, two age‐related diseases." (PMID 34197020, 2021). "Experiments in mouse model of myocarditis revealed that CLU expression was dramatically upregulated in ventricular myocytes, especially in bordering areas of inflammation and myofiber atrophy." (PMID 30235220, 2018).
preeclampsia (8 papers, 2017 to 2025). Preeclampsia is a hypertensive disorder of pregnancy that is characterized by new-onset hypertension with proteinuria presenting after 20 weeks of gestation, and depending on mild or severe forms may initially present with severe headache, visual disturbances, and hyperreflexia. "An increased level of clusterin has been confirmed in pregnancies with pathologies in pregnancy associated with preeclampsia." (PMID 36009368, 2022). "In contrast, in preeclampsia (PE) pregnancy disease, CLU expression is increased before the clinical syndrome occurs and the CLU level was positively related to the severity of PE." (PMID 37685987, 2023). "The results revealed that five out of the six serum biomarkers of kidney injury were elevated in the preeclampsia group compared to the control group (calbindin 1, clusterin, glutathione transferase pi (GSTP1), monocyte chemotactic protein 1 (MCP-1), and kidney injury molecule type 1 (KIM-1))." (PMID 40649927, 2025). "In contrast, it has been reported that serum concentrations of clusterin are significantly upregulated in women with preeclampsia, compared with normal pregnant women, indicating the increase in aggregated proteins in the serum of women with preeclampsia." (PMID 33670947, 2021). "Clusterin levels increase in preeclampsia, even prior to onset, so it may also serve as a predictive marker." (PMID 29200898, 2017). "In a recent study, the elevation of clusterin levels was observed prior to onset of preeclampsia, suggesting that it may also serve as a predictive marker of adverse pregnancy outcomes." (PMID 29200898, 2017). "Additionally, the serum concentrations of calbindin 1, clusterin, GSTP1, and KIM-1 were significantly higher in both early-onset and late-onset preeclampsia compared to the control group." (PMID 40649927, 2025). "In preeclampsia, the peripheral subpopulation of “non-classical” CD16+ monocytes, which express CX3CR1, is increased in comparison to uncomplicated pregnancies, and they show up-regulation of some immunomodulating factors like clusterin, lipocalin-2 and leptin receptors." (PMID 33496844, 2021).
pseudoexfoliation syndrome (8 papers, 2008 to 2025). "Intriguingly, variants in CNTNAP2 were also implicated in pseudoexfoliation syndrome among patients who show a selective downregulation of clusterin (CLU) expression in their eyes." (PMID 22384383, 2012). "Given its expression in the anterior segment of the eye and the association of the protein with pseudoexfoliation material, CLU is a potential genetic factor of susceptibility to pseudoexfoliation syndrome." (PMID 18806885, 2008). "We investigated the association of genetic variants across CLU in pseudoexfoliation syndrome and analyzed molecular characteristics of the encoded protein in ocular tissues." (PMID 18806885, 2008). "Nine tag single nucleotide polymorphisms (SNPs) across CLU were genotyped in 86 cases of pseudoexfoliation syndrome and 2422 controls from the Australian Blue Mountains Eye Study cohort." (PMID 18806885, 2008). "We investigated the hypothesis that common genetic variation in CLU could explain the genetic susceptibility of individuals to pseudoexfoliation syndrome." (PMID 18806885, 2008). "Haplotype association between variants across the CLU gene and pseudoexfoliation syndrome." (PMID 18806885, 2008). "Thus, CLU is an attractive candidate genetic factor that may confer individual susceptibility to pseudoexfoliation syndrome." (PMID 18806885, 2008). "Next to the involvement of CLU in pseudoexfoliation syndrome, C3 was found to be significantly upregulated in aqueous humor in eyes of patients with pseudoexfoliation syndrome indicating an important role for complement activation during this disease." (PMID 33362763, 2020). "In summary, CLU is present in ocular tissues relevant to pseudoexfoliation syndrome, and others have shown that its titer is reduced in the aqueous humor of eyes with pseudoexfoliation." (PMID 18806885, 2008). "One CLU SNP (rs3087554) was nominally associated with pseudoexfoliation syndrome at the genotypic level (p=0.044), although not when the age of controls was restricted to those over 73 years." (PMID 18806885, 2008). "Zenkel and colleagues demonstrated that CLU mRNA is found at lower levels in anterior segment tissues of eyes with pseudoexfoliation syndrome than in glaucomatous control eyes by both quantitative reverse transcription polymerase chain reaction (RT–PCR) and in situ hybridization." (PMID 18806885, 2008). "Moreover, lower levels of clusterin are present in the aqueous humor of individuals with pseudoexfoliation syndrome compared to normal individuals." (PMID 18806885, 2008). "Allelic and genotypic analyses revealed that common variants in CLU and its promoter region do not contribute in a substantial way to the risk of pseudoexfoliation syndrome." (PMID 18806885, 2008). "Clusterin is present in ocular anterior segment tissues involved in pseudoexfoliation syndrome." (PMID 18806885, 2008). "A polymorphism in CLU might contribute to genetic risk of pseudoexfoliation syndrome, but was not relevant when the age of controls was corrected for, and was not significant in logistic regression." (PMID 33362763, 2020).
renal fibrosis (8 papers, 2013 to 2021). A final common manifestation of a wide variety of chronic kidney diseases characterized by glomerulosclerosis and tubulointerstitial fibrosis. "Here, Ang II-induced renal fibrosis was exacerbated or prevented by the loss or overexpression of clusterin, respectively." (PMID 25148511, 2014). "Furthermore, loss of clusterin accelerated Ang II-stimulated renal fibrosis and AT1R expression." (PMID 25148511, 2014). "Second, CLU functions as a defense factor to prevent renal fibrosis, the common nephropathogenesis of CKD." (PMID 28701152, 2017). "Here, we extended these findings by evaluation of the role of clusterin in Ang II-induced renal fibrosis, which is more relevant to the pathophysiology of renal diseases." (PMID 25148511, 2014). "A recent study also showed that clusterin attenuates renal fibrosis in a mouse model of unilateral urethral obstruction (UUO)." (PMID 25148511, 2014). "Hematoxylin and eosin (H&E) and Sirius red staining of renal sections showed that Ad-clusterin significantly reduced Ang II-induced tubular atrophy and renal fibrosis." (PMID 25148511, 2014). "Knockout of clusterin enhanced Ang II-induced expression of profibrotic factors and accelerated Ang II-induced renal fibrosis and damage in mice via upregulation of AT1R." (PMID 25148511, 2014). "The effect of clusterin on renal fibrosis was evaluated in NRK-52E cells, a cultured renal tubular epithelial cell line, using immunoblot analysis and real time RT-PCR." (PMID 25148511, 2014). "Taken together with the results of our previous study, this finding suggests that clusterin attenuates renal fibrosis through TGF-β-dependent and -independent Smad signaling." (PMID 25148511, 2014). "Collectively, these findings suggest that Ang II is central to the development of renal fibrosis and that clusterin is an important regulator of this process." (PMID 25148511, 2014). "Our previous study showed that clusterin plays a protective role in the unilateral urethral obstruction-induced renal fibrosis." (PMID 25148511, 2014). "In summary, clusterin attenuates Ang II-induced renal fibrosis by downregulating AT1R; this action is mainly mediated by inhibition of NF-κB nuclear translocation." (PMID 25148511, 2014). "Moreover, overexpressing clusterin reduces renal fibrosis in the mouse unilateral ureteral obstruction model." (PMID 32913257, 2020). "In our previous studies we demonstrated that clusterin has a protective effect against hepatic lipid accumulation and renal fibrosis; however, the role of clusterin in hepatic fibrosis is unknown." (PMID 31739636, 2019). "As a component of glomerular immune deposits, over-expressed CLU may be anti-apoptotic and pro-survival and attenuate the development of renal fibrosis." (PMID 28701152, 2017). "This study investigated the role of CLU in the transition of IRI to renal fibrosis." (PMID 27649757, 2016). "Alpha-actinin-1 and Moesin detected after 1 week of UUO may be used as potential biomarkers of tubular injury, whereas Annexin A1, Clusterin and Vimentin may be the candidate markers of renal fibrosis." (PMID 25791774, 2015). "Here, we studied how clusterin acts against Ang II-induced renal fibrosis." (PMID 25148511, 2014). "This study suggests that clusterin could be targeted for the prevention and treatment of renal fibrosis." (PMID 25148511, 2014). "Therefore, herein, we focused on the role of clusterin in Ang II-induced renal fibrosis, which is more relevant to the pathophysiology of renal diseases." (PMID 25148511, 2014). "Examples include upregulation of SOCS3, an inactivator of cytokines, SERPINA3G (Spi-2A) that protects from caspase mediated cell death, NOX2 that may protect against ischemia and oxidative stress and clusterin that protects against renal fibrosis." (PMID 24167575, 2013).
renal fibrosis (continued). "More interestingly, by immunohistochemical stain many tubules in these CLU KO kidneys are stained positively with α-SMA, suggesting an important role of EMT in renal fibrosis in these kidneys." (PMID 27649757, 2016). "Also, our PCR array reveals that MMP9 but not TGF-β may be a major fibrotic factor for CLU deficiency-induced renal fibrosis." (PMID 27649757, 2016). "Renal fibrosis and expression of AT1R was higher in the kidneys of clusterin-/- mice than in those of wild-type mice." (PMID 25148511, 2014). "In our previous study, intrarenal infusion of clusterin reduced the level of renal fibrosis and decreased PAI-1, matrix protein expression, and TGF-β/Smad3 activity in UUO mice, indicating that clusterin plays a protective role in renal fibrosis." (PMID 25148511, 2014).
thyroid cancer (8 papers, 2015 to 2025). "The analysis of CLU transcript variants expression showed a specific increase of the CLU2 in TIR3 patients with histologically proven thyroid cancer, suggesting a possible diagnostic use of CLU2 in the management of such patients." (PMID 25934174, 2015). "Three downregulated proteins (protein S [PROS1], clusterin [CLU], and leucine-rich α-2-glycoprotein 1 [LRG1]) were found to be significantly associated with poor overall survival in thyroid cancer using differential analysis and Kaplan–Meier survival analysis." (PMID 40797389, 2025). "These DEPs were involved in cancer, including thyroid carcinoma, head and neck carcinoma, and cancer of secretory structure, in which CLU, GNAS, and PKM played an indirect role in the occurrence and development of cancer." (PMID 33299887, 2020). "We statistically analyzed the relationships between recurrence risk, BRAF gene mutation, gender, age at first thyroid cancer diagnosis, tumor size, extrathyroidal invasion, lymph node metastasis, and distant metastasis as well as the expression levels of PROS1, CLU, and LRG1." (PMID 40797389, 2025). "Immunohistochemical evidence showed that the increased expression of FN1 was mainly limited to the invasive front of thyroid cancer.CLU is a glycoprotein, which is involved in many physiological and pathological processes essential to carcinogenesis and tumor growth." (PMID 35359404, 2022). "In addition, the analysis of CLU transcripts expression level showed an increase of the CLU2 transcript in the TIR 3 patients with histologically confirmed thyroid cancer." (PMID 25934174, 2015). "Despite the need to further substantiate these results in a larger and more representative cohort, and albeit the conclusion are still speculative, they provide new insights into the role of CLU as a pro-survival gene that is up-regulated in thyroid cancer." (PMID 25934174, 2015). "The prevalent CLU protein expression in the thyroid carcinoma, in agreement with results from other laboratories, suggests that CLU may play a cytoprotective role in mammalian epithelia, including thyroid, oesophagus, urethra and rete testis epithelial cells." (PMID 25934174, 2015). "In order to assess the possible role of this gene as a candidate biomarker for thyroid cancer, we investigated CLU transcript variants in neoplastic and non-neoplastic thyroid tissues by measuring protein and transcript expression by immunohistochemical and qPCR techniques." (PMID 25934174, 2015). "In contrast, CLU exhibited elevated expression levels in kidney renal clear cell carcinoma (KIRC), kidney renal papillary cell carcinoma (KIRP), thyroid carcinoma (THCA), and GBM when compared to tissues from matched control samples." (PMID 37686218, 2023). "We found that, in thyroid cancer, the expressions of FN1, APOE, and CLU were statistically significant." (PMID 33521130, 2021). "Interestingly, we found that APOE correlated with CLU via LRP2 in MCODE2, and CLU and LRP2 had common predicted miRNAs, which implicated hub genes and their potential miRNAs that might affect thyroid cancer proliferation and invasion through the extracellular matrix." (PMID 33521130, 2021). "Additionally, poorly differentiated thyroid carcinoma and PTC tumor cells at stage IV (AJCC 8th) PTC typically expressed low to moderate levels of PROS1, CLU, and LRG1." (PMID 40797389, 2025). "Despite the growing evidence of the role of CLU in the aetiology of cancer in several tissues, the regulation of its expression and functions in human thyroid carcinoma has not been investigated." (PMID 25934174, 2015).